MMP8 (matrix metallopeptidase 8)
Diseases named in the same sentence as MMP8 in open-access papers (continued):
Sharing a sentence is not in itself a finding about the gene and the disease.
atherosclerosis (continued). "Further, MMP8 has been shown to promote atherosclerosis by activating Angiotensin II, increasing inflammation, highlighting other in vivo targets to be assessed in future studies." (PMID 40991633, 2025). "Overall, our results suggest the importance of macrophage MMP8 as a potential target to treat unstable atherosclerosis." (PMID 40991633, 2025). "By our transcriptomic data (MMP-1), a significant reduction in MMP-8 levels following BP consumption suggests a stabilizing effect on vascular integrity, potentially mitigating the progression of atherosclerosis." (PMID 40722877, 2025). "MMP8, also known as neutrophil collagenase, was once thought to be expressed exclusively in neutrophil cells, but more recent researches have shown endothelial cells, VSMCs and macrophages in atherosclerosis express MMP8." (PMID 37149580, 2023). "Matrix metalloproteinase-8 (MMP8) has been previously identified as a key player in atherosclerosis and arterial remodeling." (PMID 36291087, 2022). "A relationship among MMP8 gene variation with atherosclerosis progression was also observed in a population-based study." (PMID 26848572, 2016). "During the last decade, the studies presented here have provided novel and important insight into the role of MMP-8 in atherosclerosis." (PMID 23365489, 2013). "Systemic MMP8 deficiency decreased atherosclerosis in non-irradiated MMP8KO/ Apoe-/- mice and IGF-1 administration reduced atherosclerotic burden in Apoe-/- mice." (PMID 40991633, 2025). "Notably, we have recently demonstrated that MF-specific IGF-1 overexpression leads to a reduction in atherosclerosis, a reduction in necrotic core, an increase in collagen and other features of plaque stability, and a decrease of MF MMPs, including MMP8." (PMID 40991633, 2025). "For the current study we performed experiments with irradiated BMT mice to test the effect of MF MMP8 deficiency with/without IGF-1 on atherosclerosis and plaque morphology." (PMID 40991633, 2025). "MMP8, first identified in neutrophils, is shown to be increased in macrophages in atherosclerosis." (PMID 40991633, 2025). "In addition, Mmp8 and Mmp12 levels were reduced in Trib3KO macrophages, whose depletion in human diseased arteries and animal models of atherosclerosis results in reduced plaque size and increased collagen content, therefore improving plaque stability." (PMID 36158793, 2022). "Several risk markers related to the immune response that have key roles in atherosclerosis were identified, including the top aging marker MMP8, disease markers KIR3DL1 and MAGEA6, network markers based on degree (RBM10, PJA2, and CMTM6), and network markers based on betweenness (IRAK1 and VAMP8)." (PMID 35706446, 2022). "For example, MMP8, the top aging marker, is a collagenase with proteolytic activity against matrix proteins and is an important participant in the function of the vascular system and the development of atherosclerosis." (PMID 35706446, 2022). "The study also demonstrated that hsa_circ_0004104 may contribute to the pathogenesis of CAD by upregulating of atherosclerosis-susceptible genes, such as IDO1, MMP8, CD40, and downregulating of anti-atherosclerosis genes, such as ApoA I, RNASE1." (PMID 33421993, 2021). "Gene targeting studies also demonstrated reduced atherosclerosis development in MMP8 knockout mice." (PMID 30197987, 2018). "For this purpose, we irradiated mice and utilized bone marrow transplant to understand how myeloid derived MMP8 and IGF-1 affects atherosclerosis." (PMID 40991633, 2025). "Other studies have shown that the involvement of MMPs in atherosclerosis leads to a reduction in atherosclerotic lesions when using double knockout animals for ApoE-⁄- and MMP-2-⁄-, MMP-8-⁄-, and MMP-9-⁄- and MMP-12-⁄-." (PMID 35269673, 2022). "We demonstrated that LCZ696 or valsartan treatment attenuated the expressions of pro-inflammatory cytokines, including IL-6, MMP-8 and MCP-1, suppressed atherosclerosis and increased plaque stability." (PMID 31019233, 2019).
atherosclerosis (continued). "It has been reported that systemic MMP8 deficiency markedly suppressed atherosclerosis development, however the effect of MF specific MMP8 on atherosclerosis has not been investigated." (PMID 40991633, 2025). "To determine whether liquefaction of the brain following stroke shares other characteristics with atherosclerosis we measured the levels of OPN, IL-18, MMP-2, MMP-3, and MMP-8." (PMID 30417081, 2018). "Indeed, our findings support that atherosclerosis development is accompanied by an increase in MMP-2, MMP-3, MMP-8, MMP-9, TIMP-1 and TIMP-2 levels." (PMID 25264981, 2014).
COVID-19 (32 papers, 2020 to 2025). A disease caused by infection with severe acute respiratory syndrome coronavirus 2. "MMP-2, MMP-7, MMP-8, and neuropilin-1 were positively correlated, aligning with prior findings of elevated MMPs in severe COVID-19, linked to tissue damage and repair." (PMID 40557167, 2025). "In fact, transcript levels for the pro-inflammatory cytokines TNF-α, IL-6, and MMP8 in biopsies from COVID-19-associated AKI patients were comparable to those found in normal controls." (PMID 36979824, 2023). "Along with neutrophil infiltration and its byproducts, such as reactive oxygen species (ROS), the overexpression of the MMP-2/MMP-8 axis also boosted lipid peroxidation, which may facilitate the severe loss of lung tissue in COVID-19." (PMID 39727640, 2024). "In contrast, G-MDSC from severe COVID-19 patients had increased expression of genes associated with granulocyte functions/degranulation and chronic inflammation including Arg1, MMP8, MMP9, S100A8 and A9, MPO, IL18RA, elastase, PRTN3 (azurophilic granule protein 7)." (PMID 34341659, 2021). "DPPIV, MMP-8, MMP-9, and MMP-13 levels decreased across COVID-19 variants, suggesting a reduced proteolytic and inflammatory response, consistent with Omicron’s lower severity compared to Alpha." (PMID 40557167, 2025). "In the next step of our study, after the control of COVID-19 epidemic, we plan to investigate the exact role and the mechanism of MMP8 in leukocyte adhesion." (PMID 35145983, 2022). "They stated that the detection of this protein, in addition to lipocalin 2 and matrix metallopeptidase 8, at high concentrations, in the circulation of critically ill COVID-19 patients strongly suggests neutrophil activation and degranulation." (PMID 35330391, 2022). "Searching for a marker that would improve and simplify the ranking in COVID-19, the study intended to evaluate the relationship of MMP-9 with VEGF A, BDNF, and MMP-8 with the COVID-19 severity." (PMID 36438922, 2022). "MMP-2/MMP-8 activity is involved in the lung pathogenesis of patients with COVID-19 by increasing the influx of immune cells into the lungs, secreting HLA-G, and regulating the immune response through oxidative stress." (PMID 36142454, 2022). "Taken together, our data demonstrated that both sHLA-G and sTREM-1 levels on TAF samples were elevated in COVID-19 patients and sTREM-1 positively correlated with MMP-8, while sHLA-G levels positively correlated with both MMP-2 and MMP-8 expression." (PMID 35625532, 2022). "In COVID-19, the MMP-8 gene is seen as one of the main regulators of neutrophil-driven repair of injured lungs, as the MMP-8 is released from neutrophil secondary granules, performing the role of neutrophil chemoattractant 35,36." (PMID 36438922, 2022). "MMP-8 is also relevant to COVID-19, as its target (triggering receptors expressed on myeloid cells-1) TREM1 correlates with the severity of COVID-19 patients." (PMID 35563537, 2022). "An exception was a negative correlation between MMP-9/BDNF with IL-10/IL-17 in moderately ill and a highly positive correlation of this ratio with MMP-8 in mild, moderate, and critically COVID-19 groups." (PMID 36438922, 2022). "Circulating MMP8 has been found to closely related with lung fibrosis in COVID-19 patients and serves as member of a 5-protein classifier to predict the prognosis of idiopathic pulmonary fibrosis (IPF)." (PMID 34457122, 2021). "The expression of MMP-8 in plasma from COVID-19 patients followed the same pattern of sTREM-1 levels with a significant increase in the moderate (n = 23), severe (n = 20), and critical (n = 28) COVID-19 groups, compared to controls (n = 11) and mild (n = 19)." (PMID 34960790, 2021). "Markers like neutrophil-derived effectors (RETN), lipocalin-2 (LCN2), and matrix metallopeptidase 8 (MMP8) are among the best predictors of critical illness in COVID-19 provide perhaps the most concrete evidence to date that neutrophil activation is a hallmark of severe disease." (PMID 37144176, 2023).
COVID-19 (continued). "Besides MMP-9, which has been shown to be associated with a high risk of mortality, others, such as MMP-1, MMP-2, MMP-8, and MMP-13 have also been correlated with disease severity and increased risk of death, especially during the acute phase of COVID-19." (PMID 37372128, 2023). "However, our group demonstrated that plasma expression of MMP-8 was positively correlated with sTREM-1 levels, specifically in the group of patients with severe COVID-19." (PMID 35625532, 2022). "MMP-2 and MMP-8 were unambiguously elevated proteinases in the lung of patients with COVID-19." (PMID 35625532, 2022). "Indeed, the TAF samples of COVID-19 patients presented a high amount of MMP-8, such as high levels of MMP-2." (PMID 35625532, 2022). "Indeed, the plasma expression of MMP-8 correlated positively with sTREM-1 levels, specifically in the severe COVID-19 patient group." (PMID 34960790, 2021). "Searching for a marker that could improve and simplify the estimation of COVID-19 progress and considering the predictive potency of MMP-9, the study intended to evaluate the relationship of MMP-9 with VEGF A, BDNF, and MMP-8, concerning the development, severity of disease and outcomes of COVID-19." (PMID 36438922, 2022). "Together, overexpression of the MMP-2/MMP-8 axis, in addition to neutrophil infiltration and products, such as reactive oxygen species (ROS), increased lipid peroxidation that could promote intensive destruction of lung tissue in severe COVID-19." (PMID 35625532, 2022). "Regarding the mediators related to neutrophilic activity, MMP8, lactoferrin, lipocalin-2, and MPO (all proteins potentially released by activated neutrophils) were augmented in the serum at all timepoints during COVID-19." (PMID 40710346, 2025). "IL-8, D-dimer, S100B, IL-6, Angpt-2, MMP-8, TNF-R1, u-PAR, u-PA, osteopontin, IL-13, TNF-α, pentraxin-3, P-selectin, fractalkine, and SP-D levels were elevated in critically ill COVID-19 males compared to severe cases." (PMID 39507250, 2024). "S100A8, MMP-8 and MPO are involved in lung pathology as consequences of lung tissue degradation in tuberculosis, emphysema, COVID-19 or COPD." (PMID 37375484, 2023). "Although considered plasma prognostic biomarkers, the MMP-2 and MMP-8 pathways in the lung could become the target of specific therapies, including those proposed to diminish cell infiltration, viral immunosuppression response, oxidative stress, and tissue damage during COVID-19." (PMID 35625532, 2022). "Increased activities of matrix metalloproteinase 9 (MMP-9), as well as matrix metalloproteinase 8 (MMP-8), were reported in patients with severe form of COVID-19 8,9." (PMID 36438922, 2022). "This target proteomics approach indicated that MMP-2, MMP-7, MMP-8, and MMP-14 figured out the COVID-19 perturbation with a significant increase compared to non-COVID-19 individuals." (PMID 35625532, 2022). "The study investigated the relationships between clinical, biochemical parameters and active tissue mediators (MMP-9, MMP-8, BDNF, and VEGF A), that predominate during COVID-19, depending on the stage of the disease." (PMID 36438922, 2022). "MMP8, MMP9, and S100A12, three genes that we found significantly upregulated in COVID-19 patient, are also common components in NETs, which further demonstrates the vital roles of NETs in COVID-19 development." (PMID 34457122, 2021). "Since we had evidence of increased expression of MMP-14 and MMP-7 in COVID-19 lung tissue by proteomics reanalysis, both described activation pathways that could be effective in TAF samples to produce active-MMP-2 and active-MMP-8." (PMID 35625532, 2022). "MMP-2, MMP-7, MMP-8, and MT1-MMP were increased in the lungs of patients with COVID-19." (PMID 36142454, 2022). "PCA and ROC analysis (sensitivity 84–100% and specificity 80–100%) showed that MMP-8, 12, 13 could help distinguish MIS-C from acute COVID-19 and other tropical diseases with high sensitivity and specificity." (PMID 36544496, 2022).
COVID-19 (continued). "When the blood transcriptomic profiles of patients with mild COVID-19 were compared with the profiles from patients with moderate or severe COVID-19, CEACAM8, MMP8, ELANE, LTF, CEACAM6 and MPO were consistently amongst the top SDE genes, with levels increasing with severity and high LFCs." (PMID 35844004, 2022). "Considering the total protein form by ELISA, MMP-2 and MMP-8 were significantly higher in TAF from patients with COVID-19 compared to non-COVID-19." (PMID 35625532, 2022). "A combination of 3 MMPs (MMP-8, MMP-12 and MMP-13) produced an area under the curve (AUC) of 0.89–1, indicating that these MMPs could distinguish MIS-C from acute COVID-19 with 83–92% sensitivity and 80–85% specificity." (PMID 36544496, 2022). "In addition, power calculations were carried out to determine the ability of MMPs (MMP8, MMP12, MMP13) to distinguish MIS-C from acute COVID-19 and other tropical diseases." (PMID 36544496, 2022). "Furthermore, comparing non-survival with survival COVID-19 patients, we observed a significant increase in MMP-2 and MMP-8 levels in the non-survival group, compared to the survival group and the non-COVID-19 group." (PMID 35625532, 2022). "Interestingly, the listed genes reported as potent markers of critical illness in COVID-19 (CCL2, MMP8, IFI44, LCN2, SAA1) were identified by us as key regulators of both murine ALI and COVID-19-associated ARDS in human with the highest scores of degree centrality." (PMID 34807957, 2021). "NGAL is known to be inflammation-driven, and the lack of NGAL upregulation might be attributed to a lack of renal inflammation since in COVID-19 patients the mRNA levels of renal IL-6, TNFα and MMP8 were similar to controls." (PMID 34112226, 2021). "We identified higher levels of D-dimer, IL-6, IL-8, IL-13, Angpt-2, Pentraxin-3, S100B, MMP-8, and u-PAR in the plasma of critical COVID-19 non-survivors than in that of survivors." (PMID 39507250, 2024). "In the lungs of patients with non-survival COVID-19, MMP-2 and MMP-8 expression were elevated and correlated with the release of sTREM-1 and sHLA-G." (PMID 39727640, 2024). "MMP8 and other secondary granule components were found to be significantly elevated in the plasma of ICU versus non-ICU COVID-19 patients." (PMID 36622345, 2023). "Additionally, 13 of 55 angiogenic proteins including TIMP-1, uPA, VEGF, MMP-8/9, CXCL4/16, Endoglin, Angiogenin or Angiopoietin-2 were uniquely downregulated in 3-months post-COVID-19 patients without PE compared to those who suffered a PE." (PMID 38324145, 2024). "It appears partly reasonable with our results from proteomics reanalysis, which showed a significant increase in detection of MMP-2, MMP-7, MMP-8, and MMP-14, but not the expression of the MMP-9 protein, in lung tissue from COVID-19 compared to non-COVID-19 subjects." (PMID 35625532, 2022). "Regardless of the unchanged values of BDNF in different phases of COVID-19, we found a positive correlation between BDNF and MMP-9, MMP-8, and VEGF A, as well as a strong negative correlation of BDNF with IL-10 and cytokines ratios IL-10/IL-1, IL-10/IL-6, IL-10/IL-17, and IL-10/TNF-α." (PMID 36438922, 2022).
lung fibrosis (29 papers, 2005 to 2025). "SP-D, MMP8 and KL-6 are also well-studied as specific pulmonary fibrosis-associated biomarkers." (PMID 40160824, 2025). "MMP-8 expression is also increased in leukocytes in the lungs of patients with idiopathic pulmonary fibrosis compared to control lung samples." (PMID 40299554, 2025). "The elevated MMP-8 activities facilitate the etiology of numerous illnesses, such as atherosis, lung fibrosis, and septic disease." (PMID 37359526, 2023). "It was reported that dysfunction of collagen digestion enzymes (MMP2 and MMP8), and TIMP1 (a collagenase inhibitor) were associated with pulmonary fibrosis." (PMID 36717804, 2023). "Dysregulated expression of genes, including MMP8, in PBMCs of patients with idiopathic pulmonary fibrosis has been reported, and reduced CD28, ICOS, LCK, and ITK gene expression in PBMCs was associated with poor outcome in cohorts with this disorder." (PMID 29445374, 2018). "Supporting a role in inflammatory disorders that evolve to fibrosis we have demonstrated that MMP8 together with MMP9 associated with neutrophils were increased in hypersensitivity pneumonitis and correlated with the development of lung fibrosis." (PMID 26944412, 2016). "Bronchial epithelial cells in IPF lung tissue are positively stained for MMP-8 mainly in areas of severe lung fibrosis." (PMID 24828408, 2014). "Collectively, these results demonstrate that MMP-8 is an important regulator of IL-10 in vivo and point this metalloprotease as a potential therapeutic target in lung fibrosis." (PMID 20949050, 2010). "Therefore, it appears that MMP-8 can reduce the acute lung inflammatory response during lung injury but equally promote lung fibrosis." (PMID 40299554, 2025). "Previous reports provided evidence about the role of MMP-1 and MMP-8, also known as collagenase 1 and collagenase 2, respectively, in the development of idiopathic pulmonary fibrosis, ischemic stroke, small vessel stroke, acute hepatitis, and various cancer types." (PMID 36860404, 2023). "Other studies to prevent pulmonary fibrosis suggest that inhibitors of upregulated genes (MMP8, PDE4) in patients with pulmonary fibrosis might be a therapeutic target." (PMID 37893011, 2023). "In addition, MMP‐8 is strongly up‐regulated in alveolar macrophages and peripheral blood monocytes from patients with idiopathic pulmonary fibrosis." (PMID 33656791, 2021). "However, MMP-8 has been shown to have anti-inflammatory and pro-fibrotic activities in lung fibrosis." (PMID 31314805, 2019). "MMP-8 promotes lung fibrosis in mice by decreasing lung levels of MIP-1α and IP-10." (PMID 24828408, 2014). "If MMP-8 is found to have pro-fibrotic activities in human as well as murine lungs, our results may help guide future studies testing the efficacy of novel therapies targeting MMP-8 in halting the progression of lung fibrosis in IPF patients." (PMID 24828408, 2014). "In addition to its suppressive roles in cancer progression, MMP-8 is protective in bleomycin-induced lung fibrosis, ventilator-induced lung injury, periodontitis, and allergen-induced airway inflammation." (PMID 23632023, 2013). "In the experimental model, this enzyme may enhance inflammation and inflammatory-driven fibrosis cleaving IL10, MIP-1a and Cxcl10, and actually, Mmp8-null mice are protected from bleomycin-induced lung fibrosis although the molecular mechanisms are yet unclear." (PMID 26944412, 2016). "Based on these findings, MMP-8 could be a therapeutic target in lung fibrosis." (PMID 20949050, 2010). "Moreover, MMP-8 may also regulate lung permeability, which is an important determinant of outcome in pulmonary fibrosis, and apoptosis of inflammatory cells." (PMID 20949050, 2010). "Idiopathic lung fibrosis patient BALF show increased expression of MMPs, with MMP7, MMP8, and MMP9 predominating." (PMID 34512395, 2021).